SMARCA5 (SNF2 related chromatin remodeling ATPase 5)
Diseases named in the same sentence as SMARCA5 in open-access papers (continued):
Sharing a sentence is not in itself a finding about the gene and the disease.
tumor (continued). "Cell cycle proteins were evaluated based on their altered expression patterns (WAPAL, AHCTF1, etc.), phosphorylation patterns (CCNL1 T67, SMC4 S41, etc.), and inferred TF activities (SMARCA5, E2F3, etc.)in GC tumor tissues." (PMID 36788224, 2023). "Considering the tumor heterogeneity of the two clusters, we identified six prognostic genes (PIM2, PET117, SMARCA5, TAF9, ABCB10, MKP1) among the m6A-hypoxia genes and developed a scoring system to evaluate m6A modification patterns and hypoxia status." (PMID 36105819, 2022). "Consistent with the in vitro observations, upregulation of both SMARCA5 and miR-146b-5p led to greater F-GSC/MSC tumor growth that was seen with upregulation of miR-146b-5p alone." (PMID 32632040, 2020). "A high SMARCA5 expression was also correlated with larger tumor size and poor histological grade but not correlated with age and Lymph node metastasis." (PMID 39500888, 2024). "Circ-SMARCA5 and circ-NOL10 may act as tumor suppressors, while circ-LDLRAD3 and circ-RHOT1 may be oncogenes." (PMID 37587156, 2023). "SMARCA5 is another target gene of miR-660-5p that was validated in our previous study, and is member of the SWI/SNF family that induces genomic instability to affect tumor progression." (PMID 38057344, 2023). "SMARCA5 is an ISWI chromatin remodeling ATPase that belongs to the ATP-dependent chromatin remodeling complex SWI/SNF family, and is involved in tumor proliferation, invasion, chemoresistance, and progression, primarily through chromatin remodeling in DNA damage regions." (PMID 36231036, 2022). "Therefore, changing the balance of SMARCA5 and SMARCA1 levels could be a potential therapeutic strategy after confirming their opposing expression levels and functions in one given tumor." (PMID 34736517, 2021). "The decrease in expression of SMARCA5 and BAZ2A that we also identified in this lineage may primarily be influencing chromosomal stability that is a characteristic of this tumor, nevertheless no change occurred after inhibition or transfection of the miRNA." (PMID 25493074, 2014).
cancer (31 papers, 2013 to 2025). A tumor composed of atypical neoplastic, often pleomorphic cells that invade other tissues. "In contrast, Smarca5 loss in cancer cell lines (by depletion using siRNA) and in murine hematopoietic, progenitor cells as well as murine oocytes using complete knockout has been shown to negatively impact cell proliferation." (PMID 35269430, 2022). "More than fifty cancer driver genes showed gradually altered chromatin accessibility upon single and double-allele Smarca5 knockout and more than 100 driver genes exhibited differential gene expression." (PMID 35269430, 2022). "Hence, new biomarkers in cancers associated with SMARCA5 need to be discovered." (PMID 39500888, 2024). "Consistent with the molecular programs, we demonstrate for the first time that Smarca5-deficient primary cells exhibit dramatically decreased capacity to bypass senescence and immortalize, an indispensable step during cell transformation and cancer development." (PMID 35269430, 2022). "In addition, the SMARCA5 gene is a target of cancer-associating miRNA regulation." (PMID 32197313, 2020). "SMARCA5 is a key regulator of chromatin structure and plays pivotal roles in multiple repair pathways that maintain genome stability and prevent cancer." (PMID 39500888, 2024). "The results show that, except for SMAD5 and SMARCA5, the remaining four genes have significant prognostic ability in multiple cancers, while SMAD5 and SMARCA5 exhibit marginal statistical significance in survival analysis for some cancer datasets." (PMID 39186807, 2024). "It is worth noting that all mentioned genes affect CDH1 expression which is controlled by SMARCA5, a stem cells differentiation gene and cancer marker." (PMID 37972206, 2023). "Strikingly, R-loop mutation burden was significantly higher in tumors holding SMARCA4, SMARCA5 and INO80 gene deficiencies, consistent with a direct role of these activities preventing R-loop mutagenesis in cancer." (PMID 37898641, 2023). "The upregulated cancer drivers, in line with the observed Smarca5 dosage-dependent phenotypic outcomes, were principally involved in processes including apoptosis and response to cellular stress." (PMID 35269430, 2022). "Mechanistically, circSMARCA5 can bind exons 15–16 of SMARCA5 genomic DNA to form R-loops, which terminate SMARCA5 gene transcription and decrease the expression level of SMARCA5 in cancer cells." (PMID 36081987, 2022). "SMARCA5 expression was found dysregulated in many human malignant tumors, such as aggressive gastric cancer, breast cancer, or prostate cancer." (PMID 32197313, 2020). "Strikingly, all of the chromatin remodeling factors (SMARCA1, SMARCA2, SMARCA4 and SMARCA5) are shown to be differentially expressed in diverse cancer cell types." (PMID 26030138, 2015). "Hence, targeting of SMARCA5 has recently shown promise as a chemotherapeutic strategy due to increased genomic instability in cancer." (PMID 39500888, 2024). "Currently, there is only a limited knowledge of how SMARCA5, which is highly expressed in cancers and the regulatory mechanism of SMARCA5 expression upregulation in cancers remains unknown." (PMID 39500888, 2024). "Moreover, the deregulated expression of many cancer genes in our data reinforces the link between Smarca5 and the control of important cancer-related pathways." (PMID 35269430, 2022). "Since Smarca5 is overexpressed in different human cancers, we next asked whether known cancer driver genes were deregulated in the obtained gene expression and chromatin accessibility data." (PMID 35269430, 2022). "By integrating comprehensive analyses at the molecular as well as phenotypic levels, our study delineates the critical role of Smarca5 in primary cell fitness and the early stages of the cancer-like process of primary cell immortalization, characteristics relevant to cancer onset and evolution." (PMID 35269430, 2022). "Interestingly, this is in agreement with the predominantly observed upregulation of Smarca5 in human cancer." (PMID 35269430, 2022).
cancer (continued). "Hence, Smarca5 has a major impact on pathways involved in cell transformation, cancer development and evolution." (PMID 35269430, 2022). "Thus, Smarca5 plays a crucial role in key homeostatic processes and sustains cancer-promoting molecular programs and cellular phenotypes." (PMID 35269430, 2022). "As for SMARCA5, it was previously observed overexpressed in many malignant neoplasms." (PMID 34315468, 2021). "SMARCA5 expression was also analyzed in a dataset from The Cancer Gene Atlas (TCGA)." (PMID 32632040, 2020). "Furthermore, circ-SMARCA5 could sponge miR-181b-5p and miR-17-3p, which were identified to be onco-miRNAs with proliferative, invasive, and metastatic potential in cancer cells." (PMID 37587156, 2023). "Importantly, additional work has not identified recurrent mutations of SMARCA5 in AML or any malignant disease (so far analyzed by next-generation sequencing-based techniques)." (PMID 32197313, 2020). "For the remaining 17 genes, DNMT3B, RARB, SMAD5, SMARCA5, SMARCC1 and TGFBRAP1 were predicted only by our method, but various evidence suggests that they have a driving role in cancer development." (PMID 39186807, 2024). "As USP3 and SMARCA5 were required for DNA repair, which has a key role in human cancer, it is possible that USP3 promotes deubiquitination and stabilization of SMARCA5 in PCa specimens." (PMID 39500888, 2024). "Circ-SMARCA5, circ-NOL10, circ-LDLRAD3, and circ-RHOT1 were differentially expressed in patients with CRC as well as in non-cancer patients." (PMID 37587156, 2023). "This study provides new insights into the possible implication of circ-SMARCA5, circ-NOL10, circ-LDLRAD3, circ-RHOT1 in CRC progression, where they are expressed differentially in CRC patients as well as non-cancer patients (UC, polyp, and piles)." (PMID 37587156, 2023). "All circRNAs expression and CEA levels were significantly up-regulated in cancer patients (CRC, colon, rectum) as compared to healthy controls, except circ-SMARCA5." (PMID 37587156, 2023). "Circ-SMARCA5 is a typical CircRNA derived from exons of SMARCA gene, and very limited studies investigating its role in cancer have been carried out until now." (PMID 31601173, 2019). "To test whether the potential role of the USP3-SMARCA5 axis may as a target for cancer therapy, we silenced USP3 or SMARCA5 individually or together in PC3 cells or DU145 cells (B: left), and examined the cell survival following docetaxel." (PMID 39500888, 2024). "Due to the dynamic variation of the expressions of circ-SMARCA5, circ-NOL10, circ-LDLRAD3 and circ-RHOT in cancer, and non-cancer patients, these circRNAs might be prospective candidates for early diagnosis of CRC." (PMID 37587156, 2023). "The present results revealed that the expression of all studied circRNAs and CEA level were upregulated in both cancer and non-cancer patients as compared to healthy control except circ-SMARCA5 in non-cancer patients." (PMID 37587156, 2023). "The overexpression of BAZ1B, and therefore that of SMARCA5, could potentiate the function of TOP1 during DNA replication, affecting the response of cancer cells to TOP1 inhibitors and to other treatments affecting replication." (PMID 33802597, 2021). "Together, our as well as others’ data demonstrate that SMARCA5 is a valuable epigenetic target suitable for inhibitor discovery projects and subsequent validation in MDS/AML and potentially also in other types of cancer." (PMID 32197313, 2020). "Although previous functional studies have illustrated the mechanisms of several CircRNAs in hematological malignancies, the mechanism of Circ-SMARCA5, a typical CricRNA, is still not clear in these cancers, nor in MM." (PMID 31601173, 2019). "SMARCA5 and SMARCD1, two miR-100 targets belonging to the SWI/SNF protein family, have recently been shown to participate in differentiation of embryonal and cancer stem cells." (PMID 25537513, 2015).
cancer (continued). "Besides, a significant negative correlation was also found between circSMARCA5 and SMARCA5 expression in various cell lines and primary cancer tissues, which corroborates our observation that circSMARCA5 decreased the expression of SMARCA5 in cancer cells." (PMID 32838810, 2020).
infection (3 papers, 2023 to 2025). The state of being infected such as from the introduction of a foreign agent such as serum, vaccine, antigenic substance or organism. "Here, we report that HIV-1 Vpr can induce the production of TGF-β during infection, which we linked to the upregulation of ciTRAN, a proviral circRNA encoded by SMARCA5." (PMID 40632811, 2025). "During infection by viruses like HSV-1 or IAV, nuclear phosphorylated RPSA recruits SMARCA5, a process that enhances chromatin accessibility at NF-κB target gene promoters and facilitates the transcription of pro-inflammatory cytokines." (PMID 41472165, 2025). "Mechanistically, nucleus-localized RPSA is phosphorylated at Tyr204 upon infection, then recruits ISWI complex catalytic subunit SMARCA5 to increase chromatin accessibility of NF-κB to target gene promotors without affecting innate signaling." (PMID 38114488, 2023). "During infection by large DNA viruses such as HCMV and adenovirus, SMARCA5 is recruited to viral replication centers, where it facilitates viral genome replication—likely by maintaining chromatin structure around replication forks through its nucleosome remodeling activities." (PMID 41472165, 2025).
CNS tumors (1 paper, 2025). "According to these data27SMARCA5 expression is significantly higher in MB patients than normal tissue and other CNS tumors, while across different molecular MB subgroups6SHH subgroup displayed highest gene expression, suggesting a role for SMARCA5 in SHH-MB." (PMID 40681754, 2025).
neurological disorders (1 paper, 2025). "A focused examination of six AD-related genes – APOE, APP, BIN1, CLU, MAPT and PSEN1 – and SMARCA5, which has been linked to neurological disorders, revealed different expression patterns across cell types and AD." (PMID 41255979, 2025).
SMARCA5 also shares sentences with these, for which no sentence is quoted: anemia (3 papers); neurodevelopmental disorder (3); cervical cancer (2); COVID-19 (2); infertile (2); pancreatic cancer (2); acute leukemia (1); Alzheimer disease (1); Ataxia (1); atherosclerosis (1); dermatomyositis (1); developmental delay (1); erythroleukemia (1); Ewing sarcoma (1); Fanconi anemia (1); female subfertility (1); hemoglobinopathy (1); lipid metabolism disorder (1); liver cancer (1); malaria (1); non-small cell lung carcinoma (1); Obesity (1); oesophagal cancer (1); osteosarcoma (1); pancreatic ductal adenocarcinoma (1); prostate adenocarcinoma (1); prostatic intraepithelial neoplasia (1); rectum cancer (1); retinal degeneration (1); thrombosis (1).
A further 2 diseases each share a sentence with SMARCA5 in 1 paper.